PTCH1 (patched 1)
Diseases named in the same sentence as PTCH1 in open-access papers (continued):
Sharing a sentence is not in itself a finding about the gene and the disease.
cancer (continued). "Ptch-1, on the other hand, was reported to regulate cell cycle progression and high expression of Ptch-1 has been associated with metastasis in many human cancers." (PMID 26389956, 2015). "The link of Hh pathway to carcinogenesis was initially reported in Gorlin syndrome in which the mutation in the PTCH1 gene is responsible for the cancer incidence." (PMID 25369201, 2014). "BCC, one of the most common human cancers, regularly shows abnormalities of the Hh pathway arising from mutations in PTCH1 (50%), SMO (10%) and other genes, including Su(Fu)." (PMID 23303278, 2013). "Taken together, findings presented here indicate a Smo inhibitor should be considered in cancers that lack Smo or Ptch1 mutations." (PMID 22923130, 2012). "Data from the Sanger database showed the distribution of somatic mutations in Ptch1 for 860 unique cancer cell lines." (PMID 22923130, 2012). "Ptch1 or Smo mutations were undetected in examined murine and human immortalized lung epithelial and cancer cell lines." (PMID 22923130, 2012). "Additionally, we recognize a trend towards lower expression in patients compared to controls, aligning with the known function of PTCH1 and its association with cancer." (PMID 38534460, 2024). "The PTCH1 variants rs357564 and rs2236405 have been analyzed in other types of cancer and congenital diseases, and their relevance may be associated with their location in the protein structure and its interaction with the Smoothened protein." (PMID 38534460, 2024). "The relation of PTCH1 mutations and mRNA expression was studied in twenty cases of nevoid basal cell carcinoma (Gorlin) syndrome, an autosomal dominant disorder, using cancer tissue, surrounding healthy tissue, blood DNA, and skin tissue from four healthy people." (PMID 38920684, 2024). "Thus, indel mutations after S1223 were engineered in SW620 cells by CRISPR/Cas9 technology to generate isogenic cancer cell line pairs differing only in their PTCH1 mutational status." (PMID 36672319, 2023). "Interestingly, the observed number of mutations in the CTD is 2.19-fold higher than expected if each codon had an equal probability of being mutated, suggesting that the CTD is a hotspot for PTCH1 mutations in those epithelial carcinomas." (PMID 36672319, 2023). "Indeed, the high glucose consumption of cancer cells causes the extracellular medium to become more acidic and allows Ptch1 to drive the chemotherapeutic agents out of the cells." (PMID 35631574, 2022). "The protein PTCH1 was included in this study as it has previously been linked to cancer (SBA3)." (PMID 35033985, 2022). "Interestingly, PTCH1 shows the highest mutation rate in 7% (127/1867; 7%) of cancers, followed by PDGFRA (89/1867; 5%), ABL1 (68/1867; 4%), FOSB (56/1,678, 3%), ALDH1A1 and CCND2 (48/1,678; 2.9%), (55/1867; 2.9%)." (PMID 36704357, 2022). "Accordingly, metabolic alterations due to a single copy loss of Ptch1 in Ptch1+/−/ODCt/C57BL/6 heterozygous mice may provide insights about the cancer prone phenotype of BCCs in GS patients, including biomarkers/targets for early intervention." (PMID 31506465, 2019). "Pathogenic Hh pathway activation may occur in cancer at several levels of the Hh signal transduction cascade, including mutations in Ptch1, Smo, and Sufu, as well as amplification of Gli1." (PMID 31137846, 2019). "Moreover, the HH pathway has been linked to a population of cells called cancer stem-like cells (CSCs) which is a major contributor of therapy resistance, while PTCH1 is often associated with cancer stemness." (PMID 31200527, 2019). "Thus, the Ptch1+/− mouse has provided a useful model for directly assessing the cancer risk from low-dose and low-dose-rate radiation exposure by using a genomic signature of radiogenic cancer." (PMID 41007286, 2025). "Hence, the scenario described in the previous study may potentially be relevant to specific circumstances, such as certain cancer cells where Hh signaling is triggered by mutations downstream of Ptch1." (PMID 38664376, 2024).
cancer (continued). "Our previous work has revealed that PTCH1, a Hedgehog receptor which is expressed in many aggressive cancers, plays a role in transporting chemotherapeutic drugs out of cancer cells and contributes to their resistance to chemotherapy." (PMID 42001685, 2026). "PTCH1 transports drugs via the proton motive force using the 'reverse pH gradient', which makes its drug efflux activity specific to cancer cells and PTCH1 a highly relevant and specific new therapeutic target for cancer treatment." (PMID 42001685, 2026). "Genetic variants, mRNA expression dysregulation, and epigenetic modifications in PTCH1 have been described across diverse cancer types." (PMID 38534460, 2024). "Previous studies about PTCH1 mRNA and protein expression have reported wide differences in expression levels among diverse types of cancer and tissues." (PMID 38287479, 2024). "The present study has identified 4 cancer driver genes (PTCH1, DNMT3A, PTPRS, JAK2) that rank highest in responders and are linked to enhanced survival in the validation cohort, either as individual markers or as part of a grouped marker panel." (PMID 38951894, 2024). "Several recent studies also have shown that GLI can be activated by oncogenic pathways such as KRAS and TGF-β, independently of the Hh ligand-PTCH1-Smo route in cancer cells." (PMID 38225225, 2024). "Our findings also indicate that cancer cells with truncation of the PTCH1 CTD display increased fitness than cells carrying wild-type PTCH1." (PMID 36672319, 2023). "In this study, we present evidence for the first time that mutations in the CTD of PTCH1 prevent interaction with ATG101 and enhance the proliferation and survival of cancer cells under nutrient stress." (PMID 36672319, 2023). "Basal cell carcinomas (BCCs), the most common type of human cancer, are known to be caused by activation of the hedgehog pathway, via loss of function mutations of PATCHED-1 (PTCH1) or gain of function mutations of SMOOTHENED (SMO)." (PMID 36864465, 2023). "Several investigations have demonstrated that GANT61 significantly decreases the transcriptional production and gene expression of Gli1, PTCH1, and other Hh pathway target genes, as evidenced by inventoried Gli assays in a range of cancer cell types." (PMID 37240209, 2023). "Targets miR-425-5p which also targeted PTCH1, affecting the Hedgehog pathway, thus increasing cancer stemness and chemoresistance to cisplatin." (PMID 35978835, 2022). "PTCH1 gene showed the highest expression level in cancer tissue when we compared it to normal endometrium tissue with medium to high intensity." (PMID 36704357, 2022). "In both the pan-cancer cohort and a subset of CRC patients, those harboring the PTCH1 mutation also had better survival outcomes (P = 0.004, HR, 0.485, 95% CI, 0.337–0.697; P = 0.022, HR, 0.29, 95% CI, 0.139–0.607)." (PMID 34028566, 2022). "The discovery of this clear connection between biallelic loss of function PTCH1 mutations and BCC development was the first of many links to be made between aberrant Hh pathway activity and cancers." (PMID 36010600, 2022).
cancer (continued). "The mutation NM_000264.5(PTCH1):c.3941C>T in the gene PTCH1 is registered in ClinVar and COSMIC databases as a pathologically relevant variant (score 1.00), associated with a high risk of different malignant tumors." (PMID 35982978, 2022). "In the study, we evaluated the association of PTCH1 mutations with CRC immunity based on our single-center cohort and multiple cancer genomic datasets." (PMID 34028566, 2022). "In adults, Ptch1 is poorly expressed in healthy cells and functions as a drug efflux pump only in cancer cells." (PMID 35631574, 2022). "For example, mutations in PTCH1 and SMO were found to be mutually exclusive in the MB SHH cancer type." (PMID 34615983, 2021). "HH pathway has been investigated for potential therapeutic antagonists as a strategy for cancer treatment, although the focus is limited to ligand-dependent effectors such as Patched 1 (PTCH1) and Smoothened (SMO); Frizzled class receptor." (PMID 33494284, 2021). "Increased Shh expression can promote the autocrine Hh-GLI pathway activation of cancer cells and stromal cells through repression of PTCH1 and increase SMO activation, thus leading to transcriptional activation of Hh target genes and carcinogenesis." (PMID 34572373, 2021). "miR500A induces the Hedgehog signalling pathway by regulating the mRNA degradation of PTCH1, subsequently promoting cancer cell invasion." (PMID 33713376, 2021). "At stage 3, STARD13, CBFA2T3, RECK, and SASH1 had strong accordant/discordant effects on expression of genes in cancer, while APC, EXT1, NBL, KLK10, and PTCH1 had very weak accordant/discordant impacts on expression of genes in cancer." (PMID 33580150, 2021). "We recently discovered that the Hedgehog receptor Ptch1, which is overexpressed in many cancers, has an efficient drug efflux function in cancer cells." (PMID 33810240, 2021). "We developed screening tests to identify molecules that inhibit the resistance to doxorubicin (dxr), a chemotherapeutic agent used to treat many cancers, conferred by human Ptch1 to yeast, and the efflux of dxr by Ptch1." (PMID 32751066, 2020). "This makes Ptch1 a particularly relevant therapeutic target, and Ptch1 drug efflux inhibitors particularly interesting due to their specificity for cancer cells." (PMID 32751066, 2020). "This allows Ptch1 to efflux drugs, at the expense of proton consumption, from the extracellular medium of cancer cells where the extracellular pH is acidic due to the strong glucose consumption (Warburg effect)." (PMID 32526884, 2020). "Inactivation of the PTCH1 gene (73%) is known as inactivation of the tumor suppressor gene in BCC, and other cancer-related gene mutations that cause BCC carcinogenesis include SMO activation mutations and negative regulators of the Hh pathway." (PMID 33066274, 2020). "We found higher expression of Patched1 (PTCH1), Shh, Sufu, Smo, Gli1, Gli2 and Gli3 both at mRNA and protein levels than adherent cancer cells." (PMID 32575925, 2020). "We previously showed, for the first time, that Ptch1 has a drug efflux activity and contributes to the resistance of cancer cells to chemotherapy." (PMID 32526884, 2020). "In a study published in 2012, Bidet and colleagues showed for the first time that Ptch1 is a multidrug transporter involved in the resistance of cancers to chemotherapy." (PMID 30110910, 2018). "Screening of chemical libraries have identified several molecules that are able to enhance the cytotoxic effect of different chemotherapeutic agents by inhibiting Ptch1 drug efflux activity in different cancer cell lines that endogenously over-express Ptch1." (PMID 30110910, 2018). "Together, these data suggest that miR-212 directly targets Ptch-1 and increases cancer cell proliferation and invasion." (PMID 29899399, 2018).
cancer (continued). "Ptch1 drug efflux activity is then specific to cancer cells, in contrast to ABC transporters efflux activity, which also occurs in normal tissues." (PMID 30110910, 2018). "Ptch1 drug efflux inhibitors potentially represent much more cancer-specific and less toxic therapeutics than ABC transporters antagonists." (PMID 30110910, 2018). "Target genes of hedgehog signaling include GLI1, PTCH1 as well as other molecules involved in regulation of cancer cell function, such as ABCG2." (PMID 28404967, 2017). "By exome sequencing, we identified novel, frequent frameshift mutations in four cancer-critical genes (CRTC1, BCL9, JAK1, and PTCH1)." (PMID 28539123, 2017). "PTCH-1 overexpression in many epithelial-derived cancers correlates to overexpression of other “Hh pathway” members and promotion of an alternate epidermal cell fate decision that potentiates SCC formation." (PMID 28246447, 2017). "It decreased GLI1 and PTCH1 mRNA expression in vitro and inhibited proliferation of several cancer cell lines." (PMID 26891329, 2016). "For instance, some germline variants in several well-known loss of function cancer driver genes such as DNM2, SMAD4, NF1, PTCH1, PTEN, SMARCB1, TSC1, cause dominant negative Mendelian diseases." (PMID 27080396, 2016). "Earlier study has revealed direct binding of PTCH1 with cyclinB1 in cancer cells, leading to delayed cell cycling." (PMID 26343727, 2015). "These drugs, such as Cyclopamine, Vismodegib etc. are only effective when a cancer cell with excessive Hedgehog pathway activation, is encountering over-expressed hedgehog ligands (SHH, IHH or DHH) or has mutated PTCH1 or SMO in membrane." (PMID 23935937, 2013). "The most commonly damaged step in Hh-driven cancers involves the poorly understood interaction between two transmembrane (TM) proteins, Patched 1 (Ptch1) and Smoothened (Smo) (reviewed in Briscoe and Therond [2013])." (PMID 24171105, 2013). "Only PTCH1 P681L was strongly associated with elevated Hh pathway activation (increased GLI1 expression), and also recurrent in a type of cancer known to be initiated and maintained by autocrine Hh signals." (PMID 24368541, 2013). "Ptch1 protein was also observed in BM-derived cells as well as in cancer cells and cyclopamine reduced the Ptch1 expression in stromal compartment." (PMID 20098680, 2010). "Furthermore, we found that truncation of PTCH1 C-tail upregulated several cancer-related pathways, including EGFR and Ras signalling and led to enhanced GLI-dependent PI3K activation, which exerted a positive feedback regulation on GLI expression and activity." (PMID 41748949, 2026). "In addition, mutations of PTCH1 and SMO are found in other types of cancer, where hedgehog signaling is activated in the epithelial cells (cancer cells)." (PMID 36864465, 2023). "With the aim of investigating whether this function of PTCH1 is important in cancer cell fitness, we first identified frameshift mutations in the CTD of PTCH1 in cancer databases." (PMID 36672319, 2023). "The identified PTCH1 p.G1212S mutation is reported in the COSMIC (Catalogue of Somatic Mutations in Cancer) database, however the function of this mutation is not investigated." (PMID 36242048, 2022). "Interestingly, overexpression of PTCH1, ABL1 and FOSB genes are reported to be associated with a low survival rate among cancer patients." (PMID 36704357, 2022). "The Hedgehog receptor Patched (Ptch1) is overexpressed in many types of cancers." (PMID 35631574, 2022). "Accordingly, Ptch1 functions as an efflux pump only in cancer cells." (PMID 32751066, 2020). "Hence, Ptch1 is a particularly relevant and highly specific therapeutic target for resistant cancers that express Ptch1." (PMID 32526884, 2020).
cancer (continued). "Ptch1 has therapeutic implications in Hh-dependent cancers by inhibiting autophagy." (PMID 33251198, 2020). "This metabolic feature makes Ptch1 drug efflux activity specific to cancer cells." (PMID 32526884, 2020). "Autophagy mediates the development of RF, and a previous study showed that Ptch1 could inhibit autophagy in Hedgehog (Hh)-dependent cancers." (PMID 33251198, 2020). "Mutant inactivating mutations (loss of function) in PTCH1, PTCH2, or SUFU, the activation of mutations in SMO (gain of function) or the amplification of GLI2 lead to the random activation of the expression of target genes in Hh, causing cancer." (PMID 33066274, 2020). "Indeed, Ptch1 pumps chemotherapeutic agents such as doxorubicin (dxr) out of cancer cells, leading to chemotherapy resistance." (PMID 32751066, 2020). "Since methiothepin strongly increases doxorubicin efficacy and specifically inhibits Ptch1 doxorubicin efflux in cancer cells, the effective dose of doxorubicin received by patients could be reduced, thereby inducing less impairment in cardiac function." (PMID 30110910, 2018). "They reported that the expression of Ptch1 in S. cerevisiae increased the efflux of doxorubicin, and conferred resistance on yeast to this chemotherapeutic agent, which is used to treat recurrent cases of cancers." (PMID 30110910, 2018). "PTCH1 has multiple splicing variants, which all share the same 3’UTR sequence, meanwhile, emerging studies have shown competing endogenous RNAs (ceRNAs) play important roles in regulating cancer progression." (PMID 29435142, 2018). "The regulation of Smo activation by Ptch1 is altered in many cancers." (PMID 30110910, 2018). "Indeed, the “reversed pH gradient” that characterizes cancer cells, allows Ptch1 to function as an efflux pump specifically in cancer cells." (PMID 30110910, 2018). "In this regard, the Smurf-mediated endocytosis of Ptch1 is an essentialsignaling event, and it is theoretically possible to block Shh function both celland non-cell autonomously using Smurf inhibitors, thus opening a new route forShh-targeted cancer treatment." (PMID 24925320, 2014). "Aberrant activation of HH signaling in human cancers could result from genetic alterations in pathway components, including PTCH1, SMO, SUFU and GLI1." (PMID 23826113, 2013). "Expression levels of SHH, PTCH1, and sFRP1 mRNA in cancer samples were analyzed with real-time PCR." (PMID 20230186, 2010). "Furthermore, PTCH1-mutated tumors had higher proportions of CD8 + T cells, activated NK cells, and M1 type macrophage infiltration, as well as elevated gene signatures of several steps in the cancer-immunity cycle." (PMID 34028566, 2022). "Briefly, Sleeping Beauty (SB)-induced mutagenesis in the Patched 1 (Ptch1) heterozygous mouse model resulted in accelerated MB tumorigenesis, with transposon common insertion sites (CIS) determined to identify candidate causative candidate cancer genes driving accelerated MB development." (PMID 34154646, 2021). "Additionally, Ptch2 fails to block changes in gene expression induced by a constitutively active form of Smo and is unable to replace Ptch1 function in Ptch1 mutant basal carcinoma cells but does preserve some ligand dependent signaling in Ptch1-null fibroblasts." (PMID 34353359, 2021). "In such a hypothesis, the inhibition of Ptch1 efflux activity by sPAH would have dual benefits: to keep the intracellular antineoplastic concentration high and to specifically increase the intracellular cholesterol concentration in cancer cells." (PMID 32526884, 2020). "We presumed that the number of cancer cells with PTCH1 c.154C > T or c.158C > T was too small and the small number of mutated cells could not represent the whole heterogeneous cancer scenario." (PMID 31704974, 2019). "Hence, there are multiple lines of evidence that suggest that Ptch1 expression may contribute to cancer resistance to chemotherapy." (PMID 30110910, 2018).